REN (renin)
Diseases named in the same sentence as REN in open-access papers (continued):
Sharing a sentence is not in itself a finding about the gene and the disease.
renal dysfunction (41 papers, 2010 to 2025). "Renal dysfunctions were associated with low-grade inflammation and activation of the renin-angiotensin-aldosterone system." (PMID 36843628, 2022). "Accumulating evidence indicates that renal dysfunction is closely associated with cardiac function in patients with HF through activation of the renin-angiotensin system, volume expansion, cytokine secretion, sympathetic nerve activation, and anemia." (PMID 36198898, 2022). "The lack of statistical power precluded the analysis of potential risk factors (i.e., duration of aortic clamping, treatment with inhibitors of the renin-angiotensin system, advanced age, and preexisting renal dysfunction) and to assess the added value of RRI." (PMID 40944074, 2025). "When microalbuminuria progresses to proteinuria and a decline in estimated Glomerular Filtration Rate (eGFR) takes place, the renal dysfunction is irreversible, although inhibition of Renin-Angiotensin-Aldosterone System (RAAS) can slow down the progression." (PMID 35813092, 2022). "Renal dysfunction in EAST/SeSAME patients results in loss of Na+, K+, and Mg2+ with urine, activation of the renin–angiotensin–aldosterone system, and hypokalemic metabolic alkalosis." (PMID 35370765, 2022). "Renal dysfunction promotes thrombosis by an increase in platelet activity, activation of the renin–angiotensin–aldosterone system (RAAS) and alteration in blood vessel wall contractility due to inflammation resulting in prothrombotic state." (PMID 34772351, 2021). "The relationship between intestinal microflora and renal dysfunction is mainly through malnutrition, SCFAs, the gut renal axis, the renin–angiotensin system, the inflammation and immune response, and uremic toxins." (PMID 35273491, 2021). "The beneficial effects of the renin-angiotensin system (RAS) inhibitors for renal dysfunction and vascular adverse events are widely recognized." (PMID 20470427, 2010). "Elevated CVP can also stimulate the renin–angiotensin–aldosterone system (RAAS), induce systemic and renal inflammation, increase endothelial permeability, and elevate sympathetic outflow, compounding the risk of renal dysfunction and AKI." (PMID 40075778, 2025). "In fact, a low cardiac output secondary to systemic ventricular dysfunction may result in intraglomerular hemodynamic changes, renal hypoperfusion, sympathetic nervous and renin-angiotensin-aldosterone system activation, and renal dysfunction." (PMID 39598107, 2024). "In addition, the change of RDW is affected by many factors, such as liver or renal dysfunction, malnutrition, cancer, thyroid disease, acute or chronic inflammatory response, use of some medications, renin-angiotensin system activation, and ethnicity." (PMID 27936006, 2016). "Renal dysfunction may contribute to endothelial injury through multiple mechanisms, including activation of the renin-angiotensin-aldosterone system, heightened inflammatory responses, and increased oxidative stress, all of which can exacerbate microvascular damage." (PMID 40917659, 2025). "Predictors of mortality included age, male sex, reduced functional capacity, renal dysfunction, and absence of renin–angiotensin system inhibition." (PMID 34884277, 2021). "It has been thought that TIPS placement improves renal function and glomerular filtration by decreasing the release of renin, aldosterone, and noradrenaline —an effect that will not have a great impact on cirrhotic patients without baseline renal dysfunction." (PMID 34567562, 2021). "Type D personality was associated with lower hemoglobin levels at 12-months follow-up, independent of baseline renal dysfunction, gender, time since diagnosis, medication affecting the renin-angiotensin system, body mass index and NYHA functional class." (PMID 23472188, 2013).
viral infection (39 papers, 2018 to 2025). "However, weight loss can be associated with either a viral infection or renin-angiotensin system since ACE2 needs to balance AngII levels." (PMID 35118120, 2021). "The predictive values of orexin A, substance P, bradykinin, and DABK and the complex interplay between the renin–angiotensin system and the orexinergic system in severe, critical illnesses or viral diseases will be investigated in future studies." (PMID 40529720, 2025). "The MAS1 receptor, part of the renin-angiotensin system, has implications in inflammation and cellular stress responses, which are often manipulated by viral infections." (PMID 39495380, 2024). "Hypercoagulability phenomena induced by this viral infection appear to be related to altered von Willebrand factor activity, alteration of the renin–angiotensin–aldosterone system, and dysregulation of both innate and adaptive immunity." (PMID 37686216, 2023). "Subsequently, changes to ACE2 expression during viral infection can lead to an imbalance in renin-angiotensin system (RAS) signaling contributing to the manifestation of clinical symptoms such as excessive inflammation, myocardial injury, and lung injury." (PMID 35756893, 2022). "As a result of viral infection, the renin-angiotensin–aldosterone system becomes dysfunctional and acts as a potent pro-oxidant in blood vessels." (PMID 35204067, 2022). "ACE2 is the host receptor for SARS-CoV-2 virus, and it is also part of the renin-angiotensin system which is crucial in tissue response to viral infection." (PMID 35000578, 2022). "A focus was particularly drawn on the renin-angiotensin system, which plays a prominent role in the virus infection, and we compared the gene expression levels of receptors and proteases related to SARS-CoV-2 infection in the samples." (PMID 34947909, 2021). "Direct virus damage coupled with indirect effects of viral infection including thromboinflammation, dysfunction of the immune system, and dysregulation of the renin–angiotensin system leads to multiple organ failure." (PMID 32940201, 2020). "In contrast, triterpenoid-type compounds (e.g., GPM24, GPM30, GPM32) interacted with a separate subset of targets including ACE, AGTR2, VDR, and were more involved in cardiovascular and renin–angiotensin system-related pathways, as well as metabolic and viral disease modules." (PMID 41471341, 2025). "The decline in ACE2 activity during viral infection might exacerbate the renin–angiotensin–aldosterone system (RAAS) dysfunction, altering the body’s fluid/electrolyte balance and blood pressure, aggravating infection symptoms." (PMID 37383271, 2023). "PM2.5 penetrates the peripheral air spaces and, through the interaction with the lung renin–angiotensin system (RAS) may facilitate viral infection." (PMID 34637085, 2022). "Besides direct viral infection, indirect mechanisms such as thromboinflammation, dysfunction of the immune system, dysregulation of the renin–angiotensin system, and therapeutic effects lead to multiple organ dysfunction." (PMID 32940201, 2020). "The upregulation of ACE2 by estrogen, X chromosome inactivation, or decreased ACE2 methylation is hypothesized to offer an advantage to females over males by maintaining fundamental renin-angiotensin system-regulatory axis equilibrium after viral infection, including physiological ACE1:ACE2 ratios." (PMID 36656980, 2023). "As an indirect mechanism, the down-regulation of ACE2 and the subsequent activation of the renin–angiotensin–aldosterone system induced by the viral infection may contribute to the local and systemic inflammatory response, which damages the tissue and triggers the release of biomarkers." (PMID 34205536, 2021). "Thus, not only ACE2 but the whole renin-angiotensin regulatory pathway might be a target of the SARS-CoV-2 virus; therefore, at least renin function should be investigated to understand the pathophysiology of this viral infection." (PMID 33203793, 2020).
viral infection (continued). "First, we found an early and drastic drop in the level of renin, an upstream player in the RAS enzymatic cascade, suggesting a possible slowdown effect against the viral infection." (PMID 36851710, 2023). "At the molecular level, the renin-angiotensin system (RAS) is heavily involved in the pathogenesis of this illness, much as it is in the acute phase of the viral infection." (PMID 35566253, 2022). "However, the general inflammatory response to virus infection impairs BBB integrity, leading to the massive infiltration of renin–angiotensin components into the brain." (PMID 37568451, 2023). "First, as ACE2 is known to regulate the renin-angiotensin system (RAS), a reduction in ACE2 function after viral infection could result in a dysfunction of the RAS, which influences fluid/electrolyte balance." (PMID 34021206, 2021).
Cirrhosis (38 papers, 2006 to 2025). A chronic disorder of the liver in which liver tissue becomes scarred and is partially replaced by regenerative nodules and fibrotic tissue resulting in loss of liver function. "In large human observational studies of cirrhosis, plasma renin levels have been found as independent risk factors for the first decompensation event, hyponatremia, hypotension, and mortality." (PMID 38891995, 2024). "The high plasma NE levels correlate significantly with vasopressin levels and in cirrhosis with ascites they are associated with high plasma renin and aldosterone levels, as a consequence of an activated renin-angiotensin-aldosterone-system." (PMID 36743678, 2022). "Previous studies have already shown that the administration of NSAIDs to patients with cirrhosis, ascites, and high plasma renin activity and norepinephrine is associated with a reduction in renal perfusion and GFR and ARF." (PMID 27713354, 2010). "The increased portal pressure from cirrhosis causes splanchnic vasodilation and activates vasoconstrictive pathways such as the renin–angiotensin–aldosterone system (RAAS), leading to fluid retention, ascites, and potentially pericardial effusion due to elevated hydrostatic pressure." (PMID 39780164, 2025). "Over the past several decades, further research has revealed that both renin and AngII are elevated in cirrhosis-related renal dysfunction." (PMID 38891995, 2024). "An early study identified decreased renal perfusion as a trigger for increased plasma renin levels in cirrhosis-related kidney injury." (PMID 38891995, 2024). "While contributions from renin and AngII (classical pathway) are well-defined in cirrhosis-related renal dysfunction, the role of the alternative pathway is less clear." (PMID 38891995, 2024). "Clinicians would also face challenges in interpreting one-time plasma renin levels of individual patients with cirrhosis, particularly considering the predicted difficulty of standardizing reference ranges." (PMID 38891995, 2024). "Although not extensively studied in clinical trials, the main beneficial action of blocking the renin–angiotensin pathway in patients with cirrhosis and PH is to reduce fibrosis." (PMID 38860875, 2024). "The result of this is an increase in plasma renin, which is better established in heart failure but has also been documented in cirrhosis." (PMID 38891995, 2024). "Among cirrhosis patients with SBP, IV albumin can increase the mean arterial pressure (MAP), and decrease the serum renin and heart rate (HR), thus showing a significant improvement in the circulatory dysfunction among cirrhosis patients." (PMID 36721617, 2022). "Given that the renin-angiotensin aldosterone system is involved in chronic tissue damage and diverse organ dysfunction including myocardium, it is possible that DMF in cirrhosis is likely to be related to the activation of renin-angiotensin aldosterone system." (PMID 32321533, 2020). "The renin-angiotensin system (RAS) plays an important role in splanchnic vasodilatation in cirrhosis." (PMID 31607942, 2019). "Firstly, the disease process of cirrhosis entails a complex neuro-endocrine and hormonal activation, such as nitric oxide release and the renin-angiotensin system, creating a hyperdynamic circulation." (PMID 29514697, 2018). "At rest, renin was slightly higher in cirrhosis compared to controls, most pronounced in Child B patients (p<0.05)." (PMID 25279659, 2014). "The slight increase in renin, mainly seen in Child B patients, support that the patients were in early stages of cirrhosis with a beginning of hemodynamic derangement and activation of vasoactive hormones." (PMID 25279659, 2014). "We did not measure the activity of vasopressor systems in our study, but decreased levels of renin and aldosterone have been reported in patients with Child–Pugh grade C cirrhosis after plasma expansion." (PMID 18197961, 2008).
Cirrhosis (continued). "This haemodynamic dysfunction is common in patients with cirrhosis and gives rise to the compensatory stimulation of endogenous vasopressor systems such as the renin–angiotensin–aldosterone system, the vasopressin system and the sympathetic nervous system." (PMID 18197961, 2008). "Obvious differences between the patients with refractory ascites and less advanced cirrhosis are the high plasma levels of the anti-natriuretic hormones like renin, angiotensin II and aldosterone." (PMID 17257428, 2007). "Stimulation of the sympathetic nervous system and activation of the renin-angiotensin-aldosterone system play a pivotal role in the resistance to conventional diuretics in advanced cirrhosis." (PMID 17257428, 2007). "These patients with pre-ascitic cirrhosis have normal or reduced plasma renin and aldosterone levels." (PMID 17134488, 2006). "Furthermore, patients with advanced cirrhosis have a gradual vasodilatory condition that reduces the effective arterial blood volume and activation of the renin–angiotensin–aldosterone system (RAAS)." (PMID 37789279, 2023). "Previous research reported that a higher blood LBP concentration in patients with cirrhosis and ascites resulted in increased blood renin activity, and that the administration of the antibacterial drug norfloxacin decreased blood LBP concentration and renin activity." (PMID 36837869, 2023). "In advanced cirrhosis, compensatory mechanisms including up-regulation of the sympathetic nervous system and renin-angiotensin-aldosterone system exist to maintain proper cardiac output and organ perfusion; however, these compensatory mechanisms fail as cirrhosis progresses." (PMID 36983288, 2023). "The activation of the SNS in cirrhosis may promote renin secretion, but increased renal tubular sensitivity to aldosterone has been noted in cirrhosis, which may also contribute to sodium retention." (PMID 36983252, 2023). "Renin-angiotensin system is also responsible, in part, for hypervolemic hyponatremia in cirrhosis." (PMID 34131392, 2021). "In advanced cirrhosis, maladaptive neurohormonal activation (increase in arginine vasopressin and renin–angiotensin–aldosterone system) leads to increased free water retention, which may result in reduced plasma concentrations of chloride." (PMID 33933032, 2021). "However, the assessment of the presence and impact of hemodynamic dysfunction in cirrhosis is complicated, due to the instability and poor reproducibility of potential biomarkers such as plasma norepinephrine, renin activity and AVP concentration." (PMID 26378453, 2015). "Secondary hyperaldosteronism results from an excessive activation of the renin-angiotensin-aldosterone system, related to renin-producing tumors, renal artery stenosis, or overload conditions with relative hypovolemia (e.g., left ventricular heart failure, cirrhosis with ascites, and pregnancy)." (PMID 37764649, 2023). "Like CHF, SGLT2Is in cirrhosis reduced markers of Renin–Angiotensin–Aldosterone System (RAAS) activity, such as plasma renin and aldosterone." (PMID 40429923, 2025). "In cirrhosis, however, there is a lack of clarity about the effect of this excess renin and whether there is preferential selection for the classical RAS pathway or shunting to the alternative pathway." (PMID 38891995, 2024).
Primary hyperaldosteronism (38 papers, 2009 to 2025). A form of hyperaldosteronism caused by a defect within the adrenal gland. "While renovascular disease is linked to increased plasma renin activity, primary hyperaldosteronism is related with lower plasma renin activity." (PMID 39011229, 2024). "Thoracoabdominal CTA ruled out the possibilities of coarctation of the aorta, renal artery stenosis, renin-secreting tumors, and primary hyperaldosteronism as potential causes of secondary hypertension." (PMID 39119483, 2024). "Due to the lack of standard approaches to detection methods and measurement units, there is significant variability in the determination of the diagnostic value of the aldosterone-to-renin ratio (ARR) in primary hyperaldosteronism." (PMID 32025248, 2019). "In the case of primary hyperaldosteronism due to adrenal hypersecretion of aldosterone, the plasma renin level is low, whereas secondary hyperaldosteronism is caused by excessive activation of the renin–angiotensin–aldosterone system (RAAS) due to renal artery stenosis or oedematous disorders." (PMID 39807221, 2025). "Primary hyperaldosteronism (PA) was excluded based on the results of blood potassium, aldosterone, renin, and aldosterone to renin ratio, 24 h urine collection for sodium and potassium, and MRI of the adrenal glands." (PMID 39949590, 2025). "A repeat workup by endocrinology and endocrine surgery showed biochemical evidence of primary hyperaldosteronism with an aldosterone/plasma renin ratio of 36.8 and normal plasma catecholamines and metanephrines." (PMID 40125193, 2025). "The lab evaluation of the patient revealed a K+ of 3.8 mEq/L, Na + of 138 mEq/L, Renin of 2.6 mIU/L, Aldosterone of 47.3 ng/dL, consistent with primary hyperaldosteronism (PHA)." (PMID 41328200, 2025). "Primary hyperaldosteronism involves excessive aldosterone secretion from the adrenal glands, leading to elevated aldosterone and low renin levels." (PMID 40757677, 2024). "This anomaly underscores the importance of plasma renin activity as a more valuable tool for detecting primary hyperaldosteronism than PRC, as utilised in our patient's case." (PMID 38993410, 2024). "Laboratory diagnosis of primary hyperaldosteronism (PHA) is based on the determination of blood levels of aldosterone and renin and is carried out at all three stages of the diagnostic process." (PMID 32025248, 2019). "Laboratory diagnosis of primary hyperaldosteronism is based on determining blood levels of aldosterone, renin on request, potassium, and sodium." (PMID 32025248, 2019). "Patient 8 presented an increased aldosterone/renin plasmatic ratio; she performed a saline infusion test that excluded primary hyperaldosteronism." (PMID 31482957, 2019). "Exploration showed primary hyperaldosteronism (aldosterone = 2645 pmol/l, aldosterone/renin ratio = 327 pmol/MUI), with hypersecretion of glucocorticoids." (PMID 30923605, 2018). "Primary hyperaldosteronism was excluded by the aldosterone/renin activity ratio." (PMID 37274343, 2023). "Decreased values, in turn, may suggest primary hyperaldosteronism or a defect in renin synthesis or secretion." (PMID 36611307, 2022). "Biochemical assessment showed a mildly elevated calcium (11.1 mg/dL), high parathyroid hormone, and a plasma aldosterone concentration/plasma renin activity ratio of 124.5 (normal < 30), compatible with primary hyperparathyroidism with a concomitant primary hyperaldosteronism." (PMID 26161274, 2015). "Furthermore, it provides the first biological justification for use of MRB in a non-primary hyperaldosteronism population by the analysis of the BP response to different treatments with respect to plasma renin levels, indicating that sodium retention may play an important role in TRH." (PMID 27072827, 2016).